DDX27 (DEAD-box helicase 27)
Description:
Probable ATP-dependent RNA helicase. Component of the nucleolar ribosomal RNA (rRNA) processing machinery that regulates 3' end formation of ribosomal 47S rRNA.
Synonyms: RHLP; HSPC259; PP3241; dJ686N3.1; DRS1; Drs1p
Gene: Protein-coding gene on chromosome 20 (49,219,347 to 49,244,077, forward strand). Ensembl gene ENSG00000124228.
Subcellular location: Nucleus, nucleolus; Chromosome
Subcellular location (Human Protein Atlas): Nucleoli
Genetic constraint (gnomAD): Loss-of-function variants: 42 observed, 102.83 expected, observed/expected ratio (o/e) 0.41, 90% interval 0.32 to 0.53. The upper end of that interval is the gene's LOEUF score, 0.53, which puts it in group 2 of 6, group 1 being the genes least tolerant of losing a copy. Missense variants: 798 observed, 1,007.4 expected, observed/expected ratio (o/e) 0.79, 90% interval 0.75 to 0.84. Synonymous variants: 329 observed, 369.09 expected, observed/expected ratio (o/e) 0.89, 90% interval 0.81 to 0.98.
Homologues: Orthologues: macaque DDX27 (99% identical), pig DDX27 (95% identical), chimpanzee DDX27 (94% identical), guinea pig DDX27 (93% identical), rat Ddx27 (93% identical), mouse Ddx27 (92% identical), dog DDX27 (87% identical), rabbit DDX27 (81% identical), tropical clawed frog ddx27 (76% identical), zebrafish ddx27 (73% identical), Drosophila melanogaster Rs1 (48% identical), Caenorhabditis elegans ddx-27 (45% identical). Paralogues in human: DDX54 (23% identical), DDX55 (22% identical), DDX21 (21% identical), DDX3X (21% identical), DDX42 (21% identical), DDX10 (21% identical), DDX18 (21% identical), DDX47 (21% identical), DDX50 (21% identical), DDX24 (20% identical), DDX3Y (20% identical), DDX4 (20% identical), and 26 more.
Diseases named in the same sentence as DDX27 in open-access papers:
DDX27 is named in the same sentence as 25 diseases in open-access papers, as found by Europe PMC text mining. Sharing a sentence is not in itself a finding about the gene and the disease. The quoted sentences say what the papers report.
colorectal cancer (12 papers, 2018 to 2026). A primary or metastatic malignant neoplasm that affects the colon or rectum. "Meanwhile, DDX27, a critical factor in ribosomal RNA processing, has been implicated in carcinogenesis across multiple cancers, including colorectal cancer, hepatocellular cancer, and GC." (PMID 41158760, 2026). "DEAD-box helicase 27 (DDX27) had been proved to influence ribosome biogenesis and identified as a promoter in gastric and colorectal cancer associated with stem cell-like properties, while the impact of DDX27 on breast cancer prognosis and biological functions is unclear." (PMID 34362383, 2021). "DDX27 was reported to promote stem cell-like characteristics and cause poor prognosis in gastric and colorectal cancer, while the influence on stemness in breast cancer remains unclear." (PMID 34362383, 2021). "Previous studies showed that DDX27 regulated colony formation via cell cycle control and was a predictor of poor prognosis in gastric and colorectal cancer (Bear, Vonderheide & O’Hara, 2020)." (PMID 37927794, 2023). "Recently, DDX27 was also shown to have a pro‐tumorigenic function in colorectal cancer, and we observed using the TCGA data that it correlates with poor prognosis in endometrial cancer, as well as in liver and renal cancer." (PMID 33750001, 2021). "DDX27 was proved to act as a promoter in tumorigenesis by impacting stem cell-like characteristics in colorectal cancer." (PMID 34362383, 2021). "DDX27 was proved to act as a promoter in colorectal cancer by affecting the stem cell-like characteristics." (PMID 34362383, 2021). "Interestingly, DDX27 was reported to increase cancer progress and metastasis by regulating NF-κB in colorectal cancer." (PMID 34362383, 2021). "SCNN1B and DDX27 are significantly related to colorectal cancer." (PMID 32854705, 2020). "Specifically, DDX27 facilitates hepatocellular carcinoma progression via activating ERK signaling, and enhances stem cell-like features with undesirable survival outcome of breast cancer and colorectal cancer." (PMID 36246620, 2022).
hepatocellular carcinoma (6 papers, 2021 to 2026). A malignant tumor that arises from hepatocytes. "Till date, increased DDX27 levels have been correlated with poor prognosis and outcome in gastric, breast, colorectal, and hepatocellular cancer patients, indicating a positive association with carcinogenesis." (PMID 38939334, 2024). "DDX27 was reported as a promoter and a biomarker with worse prognosis in hepatocellular carcinoma and gastrointestinal cancer." (PMID 34362383, 2021). "DDX27 had been confirmed to promote the development and metastasis in hepatocellular carcinoma and gastrointestinal cancer with poor prognosis." (PMID 34362383, 2021). "Accumulative evidence suggests that DDX27 serves as an oncogene in various cancers, such as colorectal cancer (CRC), hepatocellular carcinoma (HCC), and GC." (PMID 35601484, 2022). "Existing evidence indicates that DDX5, DDX27, and DDX39 played a major role as oncogenes in gastric cancer and hepatocellular carcinoma (HCC)." (PMID 35723050, 2022).
breast carcinoma (3 papers, 2021 to 2023). "Further, we analyzed the implication of DDX27 on the prognosis in terms of different molecular subtypes and found that the shorter OS associated with DDX27 was especially showed in Luminal B breast cancer (p = 0.00083) and Basal-like breast cancer (p = 0.028)." (PMID 34362383, 2021). "DDX27 can enhance stem cell-like properties and cause poor prognosis in breast cancer, also may be expected to become a potential biomarker for breast cancer therapy." (PMID 34362383, 2021). "Hence, it is of great significance to explore the influence of DDX27 on tumorigenesis, progress and the association with stem cell-like properties in breast cancer, which might suggest a new idea for diagnosis and therapy." (PMID 34362383, 2021). "DDX27 is a member of the RNA helicase family and is highly expressed in several cancers, including breast cancer and CRC." (PMID 37370759, 2023). "Analysis based on TCGA-BRCA and breast cancer samples confirmed that DDX27 had a positive connection with the expression level of OCT4 significantly." (PMID 34362383, 2021). "A consistent conclusion that DDX27 was positively related to a worse prognosis was obtained on Kaplan–Meier plotter and breast cancer patients." (PMID 34362383, 2021). "Gene Set Enrichment Analysis (GSEA) was performed to analyze the potential molecular mechanisms of DDX27 in breast cancer." (PMID 34362383, 2021). "High expression of DDX27 was firstly reported in breast cancer with the close connection to clinicopathological factors and caused a shorter survival." (PMID 34362383, 2021). "Kaplan–Meier survival analysis were used to investigate the implication of DDX27 on breast cancer prognosis." (PMID 34362383, 2021). "Results of the UALCAN website also proved that the protein expression of DDX27 in CPTAC database was significantly higher in breast cancer than in normal samples (p < 0.0001)." (PMID 34362383, 2021). "Analysis of CPTAC database showed that high expression of DDX27 was closely related to the molecular subtypes but we didn’t get the same results in the 165 breast cancer patients." (PMID 34362383, 2021). "Aimed to excavate the influence of DDX27 on stem cell-like properties in breast cancer, we analyzed the relevance between the expression of DDX27 and stemness biomarkers in TCGA-BRCA database." (PMID 34362383, 2021). "Results of our study confirmed that DDX27 was significantly high-expressed in both bioinformatics analysis and breast cancer samples." (PMID 34362383, 2021). "As a result, DDX27 was significantly highly expressed in cancer comparing to the normal breast tissue (11/40, 27.5%) and there were 97 breast cancer samples (58.8%) with high-expressed DDX27 and 68 samples (41.2%) with low expression." (PMID 34362383, 2021). "Western blot, CCK-8 assay, Transwell assay and wound-healing assay were carried out to clarify the regulation of DDX27 on stem cell-like properties in breast cancer cells." (PMID 34362383, 2021). "Association between DDX27 and clinicopathological characteristics were performed to access the influence of DDX27 in breast cancer patients." (PMID 34362383, 2021). "GSEA was carried out to investigate the potential molecular mechanisms related to DDX27 in breast cancer based on the integrated data from TCGA-BRCA." (PMID 34362383, 2021). "In our study, DDX27 was highly expressed in both bioinformatic analysis and samples from breast cancer patients." (PMID 34362383, 2021). "In future, studies including more patients are required to investigate the effect of DDX27 in breast cancer." (PMID 34362383, 2021). "We evaluated DDX27 expression in 24 pairs of breast cancer samples via western blot assay and confirmed that DDX27 was significantly high expressed in cancer than matched normal tissue (p < 0.0001)." (PMID 34362383, 2021). "The expression of DDX27 was evaluated in 24 pairs of fresh breast cancer and normal tissue by western blot." (PMID 34362383, 2021).
breast carcinoma (continued). "We conducted Immunohistochemical (IHC) staining in paraffin sections of 165 breast cancer patients to analyze the expression of DDX27 and its correlation to stemness biomarker." (PMID 34362383, 2021). "We aimed to explore the influence of DDX27 on stem cell-like properties and prognosis in breast cancer." (PMID 34362383, 2021). "To further elucidate DDX27 as a breast cancer stem cell biotarget, we transfected over-expression and negative control plasmid into MCF-7 and T47D cells and found that SOX2 and OCT4 were up-regulated in DDX27 overexpressed cells on protein levels." (PMID 34362383, 2021). "Bioinformatic analysis according to Kaplan–Meier plotter and Log‐Rank test proved that higher expression of DDX27 was significantly relevant to worse OS in breast cancer (p = 0.0013)." (PMID 34362383, 2021). "Then, we performed IHC to assess the expression of DDX27 in 165 breast cancer patients and found DDX27 was expressed in nucleus." (PMID 34362383, 2021). "In this study, we analyzed the potential molecular mechanism related to DDX27 in breast cancer by GSEA." (PMID 34362383, 2021). "Therefore, the influence of DDX27 expression on molecular subtypes in breast cancer should be explored in a larger size of data in the future work." (PMID 34362383, 2021). "In short, DDX27 is bound up with the poor prognosis by enhancing stem cell-like properties and may become a potential therapeutic target in breast cancer." (PMID 34362383, 2021). "Therefore, we analyzed the expression level of DDX27 and its influence on breast cancer in this research." (PMID 34362383, 2021). "Therefore, high expression of DDX27 was closely connected with different clinicopathological factors and resulted in a worse prognosis in breast cancer." (PMID 34362383, 2021). "This analysis indicated that DDX27 might participate in various signaling pathways in breast cancer." (PMID 34362383, 2021). "We also investigated whether DDX27 could impact on proliferation and migration in breast cancer cells." (PMID 34362383, 2021). "Connection between DDX27 expression and hypoxia pathway might relate to oxidative stress responses in tumorigenesis in breast cancer." (PMID 34362383, 2021). "Overexpression of DDX27 could enhance the expression of biomarkers related to stemness and promote stem cell-like activities such as proliferation and migration in breast cancer cells." (PMID 34362383, 2021). "DDX27 was significantly high expressed in breast cancer compared with normal tissue." (PMID 34362383, 2021). "Hence, DDX27 can enhance the stem cell-like properties meanwhile leading to a poor prognosis in breast cancer, which means DDX27 may become a potentially significant prognosis biomarker and therapeutic target." (PMID 34362383, 2021). "Until now, the status of DDX27 expression and its implication on breast cancer remains unclear." (PMID 34362383, 2021). "In order to explore whether DDX27 affects the stem cell-like characteristics in breast cancer, we analyzed the association between DDX27 and OCT4 in 165 breast cancer patients by IHC staining and confirmed that DDX27 was positively related to the expression level of OCT4 (p < 0.0001, r = 0.428)." (PMID 34362383, 2021). "Furthermore, Gene Set Enrichment Analysis (GSEA) suggested that DDX27 might have an effect on breast cancer by various ways." (PMID 34362383, 2021). "Univariate analysis suggested that DDX27 was positively associated with larger tumor size (p = 0.0005), positive lymph nodes (p = 0.0008), higher histological grade (p = 0.0040), higher ki-67 (p = 0.0063) and later TNM stage (p < 0.0001) in 165 breast cancer patients." (PMID 34362383, 2021).
breast carcinoma (continued). "Our study suggested that DDX27 promoted the evaluation of breast cancer by influencing stem cell-like properties and the exploration of DDX27-related signaling pathways had the potential significance on figuring out the molecular mechanism of breast cancer development." (PMID 34362383, 2021). "The Cancer Genome Atlas-Breast Cancer (TCGA-BRCA) database and the Clinical Proteomic Tumor Analysis Consortium (CPTAC) database were used to analyze the expression of DDX27 in breast cancer." (PMID 34362383, 2021). "We also found that DDX27 was relevant to PI3K-AKT-mTOR pathway, which could act as a therapeutic targe and might provide new ideas for treatment of breast cancer." (PMID 34362383, 2021). "Enhancement of NF-κB pathway perhaps indicates that DDX27 might facilitate the processes of Epithelial–Mesenchymal Transition (EMT) and have effects on the therapeutic drug resistance in breast cancer." (PMID 34362383, 2021).
endometrial cancer (2 papers, 2021 to 2025). Primary or metastatic malignant neoplasm involving the endometrium (mucous membrane that lines the endometrial cavity). "The cancer cell lines that had a higher prevalence of loss‐of‐function mutations in PTEN had lower expression of DDX27, and this mutually exclusive genetic interaction was particularly strong in endometrial cancers." (PMID 33750001, 2021). "Furthermore, in CRC, cervical cancer, and endometrial cancer, m6A/IGF2BP1-mediated mRNA stabilizations of DEAD-box helicase 27 (DDX27), BDNF, and SYVN1 are also vital for tumor cells to enhance epithelial–mesenchymal transition." (PMID 40584294, 2025).
gastric cancer (2 papers, 2022). A primary or metastatic malignant neoplasm involving the stomach. "Here, we elucidated the critical role of DDX27 in gastric cancer progression and found that DDX27 promoted the GC EMT process by regulating the alternative splicing of LPP." (PMID 35601484, 2022). "In summary, we unveiled that the protumorigenic function of DDX27 was mediated through a cancer-regulating functional axis DDX27/LPP/EMT in gastric cancer." (PMID 35601484, 2022). "Here, we investigated the effects and clinical significance of DDX27 in gastric cancer and proved that DDX27 could promote the migratory and invasive ability of GC through the LPP-mediated EMT process." (PMID 35601484, 2022). "DEAD-box helicase 27 (DDX27) was previously identified as an important mediator during carcinogenesis, while its role in gastric cancer (GC) is not yet fully elucidated." (PMID 35601484, 2022). "A positive correlation between DDX27 and LPP was observed in the TCGA gastric cancer cohort." (PMID 35601484, 2022).
chronic kidney disease (1 paper, 2022). Impairment of the renal function secondary to chronic kidney damage persisting for three or more months. "DDX27 was significantly up-regulated in chronic kidney disease than normal kidneys, and was negatively correlated to body mass index." (PMID 36246620, 2022).
cognitive decline (1 paper, 2022). "Mapping of GWAS results identified genes that have been previously associated with cognitive decline including STAU1, SEMF3A, IP6K1, MST1, the ATNX2/BRAP locus, ALDH2 and DDX27, where a likely functional missense variant is highly associated." (PMID 35052462, 2022).
colon cancer (1 paper, 2018). "Lower DDX27 expression was found in colon cancer than in rectal cancer (P < 0.001), an observation verified in TCGA cohort (P < 0.001)." (PMID 29535419, 2018). "DDX27 expression in primary colon cancer was an independent prognostic marker for survival in both Beijing cohort (P < 0.05; hazard ratio: 3.362; 95% CI, 1.157 to 9.771) and TCGA cohort (P < 0.05; hazard ratio: 7.345; 95% CI, 1.014 to 53.203)." (PMID 29535419, 2018). "Consistent result was obtained in TCGA cohort, in which higher expression of DDX27 predicted poor relapse-free survival in patients with colon cancer (P < 0.01)." (PMID 29535419, 2018). "This analysis showed that within colon cancer, patients whose tumor exhibited high DDX27 expression had a shorter survival (P < 0.05)." (PMID 29535419, 2018). "Prognostic value of DDX27 in primary colon cancer was further validated in a third cohort." (PMID 29535419, 2018). "We determined the mRNA expression of DDX27 in various colon cancer cell lines by qPCR." (PMID 29535419, 2018). "Moreover, high DDX27 staining predicted poor overall survival for patients with early stage (I and II) colon cancer in Shanghai cohort, as evidenced by Kaplan-Meier survival analysis (P < 0.05) and multivariate analysis (P < 0.05; hazard ratio: 1.860; 95% CI, 1.064–3.250)." (PMID 29535419, 2018).
IgA nephropathy (1 paper, 2022). "Through integration of three machine learning approaches (LASSO, SVM-RFE, random forest), we finally determined three characteristic RBPs of IgA nephropathy: DDX27, RCL1, and TFB2M." (PMID 36246620, 2022). "Especially, DDX27, RCL1, and TFB2M were significantly linked to most immune cell populations and immune checkpoints, indicating that above characteristic RBPs might participate in modulating immune cell infiltrations during IgA nephropathy progression." (PMID 36246620, 2022). "Compared with normal specimens, TFB2M, DDX27, and RCL1 expressions were significantly down-regulated in IgA nephropathy." (PMID 36246620, 2022). "After integration of above machine learning algorithms, we finally determined TFB2M, DDX27, and RCL1 as characteristic RBPs of IgA nephropathy." (PMID 36246620, 2022). "However, no studies have reported the roles of DDX27, RCL1, and TFB2M in IgA nephropathy." (PMID 36246620, 2022).
lymph node metastasis (1 paper, 2022). "Moreover, DDX27 had a positive correlation with the depth of invasion, lymph node metastasis, and distant organ metastasis (p < 0.05)." (PMID 35601484, 2022).
rectal cancer (1 paper, 2018). A primary or metastatic malignant neoplasm that affects the rectum. "Nevertheless, expression of DDX27 in both colon and rectal cancer was significantly higher than in adjacent normal tissues (both P < 0.001)." (PMID 29535419, 2018).
viral infections (1 paper, 2025). "Despite its importance in fundamental cellular functions, the role of DDX27 in host immunity or viral infections remains poorly understood, making it an intriguing candidate for further investigation in the context of viral pathogenesis." (PMID 40574840, 2025). "Despite the increasing evidence regarding the roles of DDX family proteins, the function of DDX27 in viral infection, particularly in the context of PRRSV (a virus of significant economic concern in swine) has not been previously explored." (PMID 40574840, 2025). "While DEAD-box helicases (DDXs) are known to either promote or inhibit viral infections, no prior studies have explored the role of DDX27 in viral pathogenesis." (PMID 40574840, 2025).